NR3C1 (nuclear receptor subfamily 3 group C member 1)
Diseases named in the same sentence as NR3C1 in open-access papers (continued):
Sharing a sentence is not in itself a finding about the gene and the disease.
breast carcinoma (continued). "It suggests that a global increase in DNMT3a in a highly stressed breast cancer patient might result in the silencing or downregulation of NR3C1 and interfere with the regulation of the stress response, mediated by NR3C1." (PMID 36430579, 2022). "However, studies investigating germline and somatic CNVs failed to report a loss of NR3C1 coding regions associated with breast cancer risk and prognosis." (PMID 35761157, 2022). "The glucocorticoid receptor NR3C1 is frequently downregulated in breast tumors, and there is evidence that it plays a role as a tumor suppressor in ER+ breast cancer." (PMID 40043049, 2025). "Subsequently, 10 top hub genes were identified and five (IGF1, ADIPOQ, PPARG, LEP, and NR3C1) significantly correlated with worse OS and BCSS on response to trastuzumab in breast cancer patients." (PMID 35317079, 2022). "According to the result of TF analysis, although most of the TFs have been reported to be associated with breast cancer, there were still TFs such as EOMES, POU3F2, NR3C1, and RUNX1 that were less reported in breast cancer." (PMID 36313438, 2022). "Similar to 5-HTT and NR3C1, the expression of OXTR is also related to the clinical outcomes of breast cancer." (PMID 36430579, 2022). "The glucocorticoid receptor (NR3C1, GR) is frequently downregulated in breast tumors, and evidence suggests it acts as a tumor suppressor in estrogen receptor-positive (ER+) breast cancer." (PMID 31675993, 2019). "The peptides upregulate suppressors NR3C1, BRCA1, BRCA2, SFN, and RB1, which may initiate apoptosis processes and growth regulation in breast cancer cells, potentially preventing tumor progression." (PMID 40043049, 2025). "Therefore, we considered IGF1, LEP, ADIPOQ, NR3C1, and PPARG as potential predictors for the poor prognosis of patients with breast cancer." (PMID 35317079, 2022). "Finally, the gene (FOS) from the breast cancer stage II pattern, physically interacts with JUN, a target gene of Vinblastine Breast cancer drug and with NR3C1, a target gene of Megestrol Breast cancer drug." (PMID 26892392, 2016). "Although all of the genes in this panel have been reported to have roles in breast cancer, there have been no reports of expression changes in NR3C1 and RB1CC1 genes in response to afatinib, neratinib or gefitinib." (PMID 23816254, 2013). "Furthermore, the low expression levels of ADIPOQ (HR = 0.416, p < 0.01), IGF1 (HR = 0.458, p < 0.05), LEP (HR = 0.527, p < 0.05), NR3C1 (HR = 0.457, p < 0.05), and PPARG (HR = 0.491, p < 0.05) were notably related to the poorer BCSS of breast cancer patients with tumor pathological stages III–IV." (PMID 35317079, 2022). "As with AR, GR (NR3C1) expression is not routinely evaluated in breast carcinomas." (PMID 34638457, 2021).
asthma (68 papers, 2007 to 2025). "The rs41423223247*G allele of the NR3C1 gene was associated with severe asthma in patients from Ukraine and with an increase in the number of asthma exacerbations and severe asthma in children from Egypt." (PMID 39795959, 2024). "For example, asthma drug response involves the gene encoding of the glucocorticoid receptor (NR3C1), one of the most studied genes for GCS metabolism." (PMID 39795959, 2024). "After evaluating the SNPs of NR3C1 in in vivo and in vitro models, the results showed that it was closely associated with hypersensitivity to glucocorticoids in asthma." (PMID 34055877, 2021). "GWAS (Genome-wide association studies) have found that SNPs (single nucleotide polymorphisms) located in NR3C1 were positively replicated in the corticosteroid drug pathway of asthma." (PMID 34055877, 2021). "Polymorphism Tth111I of the NR3C1 gene differentiates asthma patients according to the symptom control level based on the ACTTM test score into two subpopulations (ACTTM score <20 vs. ACTTM score ≥20)." (PMID 23407653, 2013). "In view of the results obtained for Tth111I polymorphism of the NR3C1 gene in asthma patients, additional exploration analyses were carried out within that group." (PMID 23407653, 2013). "Statistically significant differences were identified in the distribution of Tth111I polymorphism of the NR3C1 gene between asthma patients stratified according to asthma control levels based on ACTTM scores (<20 vs. ≥20; p<0.05)." (PMID 23407653, 2013). "The results in this study did not confirm previous observations on the role of BclI polymorphism of NR3C1 gene in the pathogenesis of asthma." (PMID 23407653, 2013). "While, clinical studies have reported that NR3C1 is strongly associated with asthma severity." (PMID 32512817, 2020). "Additional analyses addressing the frequencies of NR3C1 gene Tth111I polymorphism alleles and genotypes demonstrated statistically significant correlations between healthy controls and patients with asthma characterized by a control profile corresponding to an ACTTM score ≥20, as shown in Table IV." (PMID 23407653, 2013). "However, the study demonstrated a correlation between the presence of the Tth111I polymorphism of the NR3C1 gene and a specific profile of asthma control according to ACTTM." (PMID 23407653, 2013). "The aim of the present study was to assess the effect of the selected NR3C1 gene polymorphisms on the level of asthma control, as well as to identify in additional investigative studies their role in the determination of disease presentation phenotypes in particular patient groups." (PMID 23407653, 2013). "Investigative analyses demonstrated statistically significant correlations for alleles and genotypes of Tth111I polymorphism of the NR3C1 gene between healthy subjects and patients with severe asthma characterized by a control profile corresponding to an Asthma Control Test (ACT)TM score ≥20." (PMID 23407653, 2013). "Additionally, correlations were demonstrated between the presence of the Tth111I NR3C1 gene polymorphism in the patient group and the disease severity and higher asthma control level based on ACTTM scores." (PMID 23407653, 2013). "Saygideger conducted a meta-analysis and revealed that childhood trauma induces asthma or other chronic inflammatory diseases by influencing genes such as NR3C1 and FKBP5, which mediate immune inflammation." (PMID 36458128, 2022). "In this study, blood from healthy volunteers, burn and asthma patients, as well as from peripheral blood mononuclear cells isolated from leukoreduced donor whole blood, were screened for NR3C1 isoforms." (PMID 30736733, 2019). "Three of the predicted target genes, namely ATXN1, NR3C1 and PTEN, have previously been associated with asthma." (PMID 26693910, 2015). "The AA ER22/23EK, AA N363S and CC BclI haplotype of the NR3C1 gene was identified to significantly aggravate trait anxiety in patients with asthma (P=0.026)." (PMID 25009637, 2014).
asthma (continued). "The NR3C1 gene and its transcripts are key factors involved in the inflammation of asthma and are responsible for alterations in the functioning of the GR." (PMID 25009637, 2014). "The consistency of genotype distribution in the control and asthma groups with Hardy-Weinberg equilibrium was demonstrated only for the ER22/23EK SNP of the NR3C1 gene." (PMID 23407653, 2013). "In addition, studies have found that the glucocorticoid receptor (GR) encoded by the NR3C1 gene, as a core regulator of immune and inflammatory response, is a therapeutic target in asthma and other chronic inflammatory diseases." (PMID 41403444, 2025). "Notably, Mmp2 and Nr3c1 are two hub nodes, which are members of both component targets and asthma targets, making them crucial, accounting for PT in asthma treatment." (PMID 33133221, 2020). "Similarly, NR3C1, a glucocorticoid receptor, was activated by drugs indicated in asthma but potentially harmful for hypertension." (PMID 31705029, 2019). "To better understand the impact of hGR variations, we have explored the NR3C1 gene in two populations: volunteers (i.e., healthy adults) and people suffering from burns or asthma (i.e., medical conditions that have variable responsiveness to glucocorticoid treatment)." (PMID 30736733, 2019). "The remaining 4 target genes were assessed based on previous literature: ATXN1 has been associated with asthma, NFAT5 is implicated in the regulation of proinflammatory cytokines, NR3C1 is a target for steroid-based asthma treatments and TAB2 is a validated miR-155-5p target." (PMID 26693910, 2015). "The results of the current study confirmed that all NR3C1 polymorphisms (haplotype, ER22/23EK, N363S and BclI) participate in the regulation of the intensity of trait-anxiety in asthma patients, which significantly correlates with increases in airflow obstruction." (PMID 25009637, 2014). "It was established that only the Tth111I polymorphism of the NR3C1 gene plays an important role in the pathogenesis of chronic bronchitis leading to the development of asthma with both allergic and non-allergic etiology." (PMID 23407653, 2013). "It was established that the Tth111I polymorphism of the NR3C1 gene plays an important role in the pathogenesis of chronic bronchitis leading to the development of asthma with both allergic and non-allergic etiology." (PMID 23407653, 2013). "It is worth noting that the current study highlights the lack of association between polymorphic forms ER22/23EK of NR3C1 gene in the pathogenesis of asthma." (PMID 23407653, 2013). "Th2 cells had the highest level of expression of NR3C1 compared to other inflammatory cells, which may explain the effective control by steroids of Th2 immune responses, a dominant feature in mild-to-moderate asthma." (PMID 34395637, 2021). "Therefore, the NR3C1 gene substantially modified the level of trait anxiety in asthma sufferers." (PMID 25009637, 2014). "Allele A of the Tth111I NR3C1 gene polymorphism was demonstrated to be an important factor correlating with the risk of development for specific disease phenotypes (severe asthma with ACTTM score ≥20, severe non-allergic asthma with ACTTM score ≥20 and severe allergic asthma with ACTTM score ≥20)." (PMID 23407653, 2013). "Despite these limitations, our study identifies seven core targets (HSP90AB1, CCNB1, CCK, CDK6, CASP9, NR3C1, and ERBB2) that offer promising avenues for developing novel asthma therapies." (PMID 41403444, 2025). "Protein-protein network analysis demonstrated that ANXA1 interacts directly with genes enriched for asthma (including IL4 and IL13) and inflammatory regulation (NR3C1, glucocorticoid receptor) showing its significance in dysregulation of the immune response." (PMID 37227431, 2023). "Further investigation of the biological function of ANXA1 revealed that it interacts with genes enriched for asthma (including IL4 and IL13) and inflammatory regulation (NR3C1, glucocorticoid receptor)." (PMID 37227431, 2023).
asthma (continued). "The combined interaction scores resulted in higher interactions for the genes STAT3, AGO2, COL1A1, CLCN6, and KSR for moderate asthma and JAK2, INSR, ERBB2, NR3C1, and PTK6 for severe asthma." (PMID 32512817, 2020). "Glucocorticoids act on the glucocorticoid receptor (GR; NR3C1) to resolve inflammation and, as inhaled corticosteroids (ICS), are the cornerstone of treatment for asthma." (PMID 30704470, 2019). "Glucocorticoids act on the glucocorticoid receptor (gene NR3C1) to reduce expression of numerous inflammatory genes, and this explains their profound anti-inflammatory effects of ICS in mild-to-moderate asthma." (PMID 28107494, 2017). "Critically, NR3C1, HSP90AB1, and ERBB2 collectively suppress plasma cells (unified negative correlations), implicating synergistic control of humoral immunity dysregulation in asthma." (PMID 41403444, 2025). "Patients with moderate asthma had higher levels of NR3C1 mRNA expression compared to healthy controls, although not to a significant extent (log2 intensity 10.17 ± 0.29; p = 0.07)." (PMID 34395637, 2021). "These genes may explain certain features of asthma severity, including allergic response (STAT3) and inflammation in asthmatic airways (NR3C1 and COL1A1)." (PMID 32512817, 2020). "Previous studies on NR3C1 gene polymorphisms have failed to confirm that the ER22/23EK and BclI SNPs play any role in the etiopathogenesis of asthma." (PMID 25009637, 2014). "For example, in severe asthma, the combined interaction scores for the STAT3, AGO2, COL1A1, CLCN6, and KSR1 genes yielded a higher interaction for the moderate asthma phenotype, and the JAK2, INSR, ERBB2, NR3C1, and PTK6 genes were more interactive for the severe asthma phenotype." (PMID 32512817, 2020).
Obesity (57 papers, 2006 to 2025). Accumulation of substantial excess body fat. "Chromosome 5q also contains the gene NR3C1, which codes for glucocorticoid receptors, and its polymorphism is significantly associated with bronchial asthma and obesity, influencing the accumulation of abdominal visceral fat." (PMID 40426941, 2025). "Its relevance is supported by research findings showing that mutations or polymorphisms in the GR-encoding NR3C1 gene lead to obesity and metabolic diseases if they express a more active form of the GR protein." (PMID 36917179, 2023). "Glucocorticoid receptor (NR3C1) polymorphisms associate with obesity, muscle strength, and cortisol sensitivity." (PMID 26821164, 2016). "In the NR3C1 Bcl1 G allele carriers, variation in this receptor was associated with obesity, hypertension, and diabetes." (PMID 25944971, 2015). "Recently, we described the influence of the NR3C1-BclI polymorphism on the prevalence of obesity in adult CAH patients." (PMID 25050120, 2014). "Conversely, demethylation of nr3c1 is linked to diseases such as obesity." (PMID 40243462, 2025). "On the other hand, demethylation of nr3c1 is associated with diseases such as obesity." (PMID 40243462, 2025). "Obesity, hyperinsulinemia, and abdominal visceral fat are associated with Nr3c1." (PMID 38931172, 2024). "Similarly, Nr3c1, the glucocorticoid receptor gene, has been reported to be involved in hyperinsulinaemia, fat deposition, and inflammatory responses associated with obesity." (PMID 22715380, 2012). "Variants in the NR3C1 gene have been reported in patients with MDD and obesity and found to confer reduced risk for quantitative metabolic traits and T2D in Cushing syndrome; variants have not been reported in T2D and MDD-T2D comorbid patients." (PMID 36233250, 2022). "The abundance of transcripts of HSD11B1, HSD11B2, PER1, and NR3C1 were unaffected by obesity or insulin." (PMID 33270115, 2021). "The findings that GTP supplementation into the drinking water reversed the expression levels of 11/12 genes (except Nr3c1) in obese rats corroborates the anti-obesity role of GTP." (PMID 22715380, 2012). "Nr3c1 mRNA levels have also been reported to be significantly decreased in obesity." (PMID 22715380, 2012). "The common targets of obesity, T2DM, and AS are estrogen receptor 2 (ESR2), androgen receptor (AR), CYP19A1, NR3C1, SRC, and arachidonate 5-lipoxygenase (ALOX5)." (PMID 39575382, 2024). "Altered DNA methylation in promoters of transcription factor genes (PPARA, KLF15, NR3C1, RORA and ATF4) known to regulate FGF21 expression and its binding receptors and co-factors (FGFR1, FGFR3 and FGFRL1 and KLB) has been revealed in relation to the elevated levels of circulating FGF21 in obesity." (PMID 33670024, 2021). "The core targets between estrogen and obesity are proto-oncogene, non-receptor tyrosine kinase (SRC), estrogen receptor 1 (ESR1), prostaglandin-endoperoxide synthase 2 (PTGS2), nuclear receptor subfamily 3 group C member 1 (NR3C1) and cytochrome P450 family 19 subfamily A member 1 (CYP19A1)." (PMID 39575382, 2024).
prostate carcinoma (50 papers, 2012 to 2025). A carcinoma that arises from epithelial cells of the prostate gland. "Due to the AR-mediated repression of NR3C1 expression, AR-negative prostate cancer cells exhibit higher levels of GR compared to AR-positive cells." (PMID 39027480, 2024). "NR3C1 agonists like prednisone and dexamethasone are already under usage in lymphoid cancers and can be explored as potential repurposed drug for prostate cancers." (PMID 36468011, 2022). "Further investigations with different systems biology methods have prioritized NR3C1, ABHD2, and GSK3B as potential genes involved in prostate cancer metastasis owing to their high mutation load and expression status." (PMID 36468011, 2022). "We found that NR3C1 (glucocorticoid receptor) mRNA and GR protein was expressed at moderate to high levels in a subset of the prostate cancer cell lines." (PMID 33303959, 2020). "Regulation of GR expression in prostate cancer disease progression at the GR (NR3C1) locus via AR binding and polycomb-mediated H3K27me3 repression." (PMID 28891793, 2017). "(D) ChIP-seq tracks for H3K27me3 at the GR (NR3C1) locus in normal luminal prostate organoids and advanced prostate cancer (MSK-PCa2) organoids (top), and LNAR' and LREX' cell lines maintained on and off Enz (1 uM) (bottom)." (PMID 28891793, 2017). "Characterization of a tissue-specific GR (NR3C1) enhancer in prostate cells and Enz-resistant prostate cancer." (PMID 28891793, 2017). "Furthermore, a preprint publication has proposed that ONECUT2 facilitates the development of AR-independent prostate cancer by suppressing AR signaling and facilitating NR3C1 transcription." (PMID 39027480, 2024). "Interestingly, down regulation of NR3C1 seems to improve the prostate cancer patient survival rate beyond 150 months." (PMID 36468011, 2022). "Interestingly, in 5/9 genes (55.5%), i.e., ABHD2, DICER1, GSK3B, NR3C1, and NFIB mutations were localized to functional domains of their corresponding proteins, which suggest them to be highly critical genes for prostate cancers." (PMID 36468011, 2022). "On the other hand, low expression level of NR3C1 could extend the disease-free survival rate in 45% of prostate cancer patients beyond 150 months (p < 0.05)." (PMID 36468011, 2022). "The evidence for protein NR3C1 related to prostate cancer and MAPK proteins, member of the MAP kinase family, involved in the cellular processes such as apoptosis, cell proliferation, and it also leads to G1 cell cycle arrest in prostate cancer." (PMID 22577352, 2012). "The other genes showing molecular alterations in prostate cancer samples from highest to lowest are as follows; FGF2 (94/4990; 1.9%), NFIB (86/4990; 1.7%), CEP43 (62/4990; 1.2%), GSK3B (99/8961; 1.1%), DICER1 (101/8961; 1.1%), NR3C1 (53/4990; 1.1%) and ABHD2 (28/4,990; 0.6%)." (PMID 36468011, 2022). "Bicalutamide and darolutamide but not apalutamide treatment significantly upregulated NR3C1 and SLC7A11 expression, demonstrating that AR antagonist-induced transcription in prostate cancer cells is not limited to a single AR antagonist." (PMID 31501863, 2019). "Similarly, enzalutamide stimulated transcription of NR3C1 and SLC7A11 but not PSA or TMPRSS2, suggesting that enzalutamide-stimulated transcription is not limited to a single prostate cancer cell line." (PMID 31501863, 2019).